MPC1L (mitochondrial pyruvate carrier 1 like)
Description:
Mediates the uptake of pyruvate into mitochondria.
Synonyms: SLC54A3
Tractability: Antibody: UniProt predicts a signal peptide or a membrane-spanning region.
Gene: Protein-coding gene on chromosome X (40,623,428 to 40,624,136, forward strand). Ensembl gene ENSG00000238205.
Subcellular location: Mitochondrion inner membrane
Pathways (Reactome):
Metabolism: Pyruvate metabolism
Gene Ontology:
Molecular function: protein binding; pyruvate transmembrane transporter activity
Biological process: pyruvate import into mitochondria
Cellular component: inner mitochondrial membrane protein complex; mitochondrial inner membrane
Homologues: Orthologues: chimpanzee MPC1L (99% identical), macaque MPC1L (74% identical), rat Mpc1l (63% identical), rabbit MPC1L (62% identical), pig MPC1L (61% identical), mouse Gm4984 (60% identical), guinea pig MPC1L (54% identical). Paralogues in human: MPC1 (48% identical), MPC2 (22% identical).